EGFR (epidermal growth factor receptor)
Diseases named in the same sentence as EGFR in open-access papers (continued):
Sharing a sentence is not in itself a finding about the gene and the disease.
tumor (continued). "However, we observed enhanced anti-tumor activity when both KTN3379 and cetuximab were combined suggesting that ErbB3 and EGFR act independently of each other at the receptor level." (PMID 28723928, 2017). "Although not further investigated, it seems likely that this effect is due to clonal selection processes as cells with high EGFR copy numbers are not evenly distributed throughout the whole tumor tissue." (PMID 28183348, 2017). "Compared with other anti-EGFR therapies the low toxicity and the lack of skin rash from nimotuzumab is an advantage." (PMID 29056908, 2017). "Subcutaneous tumor development of RPN2 or EGFR shRNA-mediated stable knockdown or negative control of HCT116 cells were monitored by measuring the tumor size and weight every 4 days." (PMID 29069815, 2017). "For a tumor with a smaller number of initial subclones, such as one comprised of 90% EGFRL858R and 10% EGFRL858R, T790M, all switching strategies induced a response for EGFR TKI dose reductions of up to 50%." (PMID 28287179, 2017). "In addition to its apoptosis-inducing, EGFR-blocking activity, cetuximab directs the ADCC mechanism at tumor cells, using primarily natural killer (NK) cells to maximize antitumor effects and thereby representing the first immunotherapy in SCCHN." (PMID 28536670, 2017). "Unexpectedly, the anti-diabetic drug metformin is an effective, economic and safe assistance drug for cancer, which can enhance cellular sensitivity to EGFR-TKI and may synergistically enhance the anti-tumor activity of HDACis." (PMID 29212192, 2017). "In univariate analysis, EGFR mutation was correlated with ADC pathology, non-smoker status, peripheral tumor location, and low MTV." (PMID 28422710, 2017). "Moreover, in order to provide the vehicle with tumor targetability, aptamer molecules against the EGF receptor (EGFR) were conjugated to the liposomal surface." (PMID 28842588, 2017). "Importantly, FAM83A interacts with c‐RAF and PI3K p85 components of the EGFR pathway, and FAM83A expression was correlated with tumor growth rate." (PMID 28078827, 2017). "A total of 2,014 patients with stage IV NSCLC without known EGFR or ALK genomic tumor aberrations initiated systemic anticancer therapy, 22% with squamous and 78% with nonsquamous histology." (PMID 28644837, 2017). "We demonstrate that ENb-TRAIL engages both EGFR and DR5 simultaneously to form EGFR-ENb-TRAIL-DR5 complex, resulting in DR5 clustering at the plasma membrane and subsequent induction of caspase-mediated apoptosis in vitro and in mouse tumor models." (PMID 28572590, 2017). "Gene copy number alteration is one mechanism for overexpressing the EGFR protein and was also demonstrated to be related to lymph node metastasis, tumor invasiveness and perineural invasion." (PMID 28854970, 2017). "Even though overexpression of EGFR and Yki resulted in a very similar growth phenotype, inactivation of BAP subunits drove tumor formation in discs expressing Yki but not in discs expressing EGFR." (PMID 28754838, 2017). "Our finding that PAD2 appears to function within the EGF signaling pathway to modulate DCIS tumor cell migration suggests that PAD2 and/or citrullination may have predictive power for identifying aggressive EGFR+ DCIS lesions." (PMID 28549415, 2017). "The Hsp90 inhibitor AT13387 could inhibit NPC C666-1 cell growth and induced cellular senescence with the downregulation of multiple Hsp90 client oncoproteins EGFR, AKT, CDK4, and significantly suppressed tumor formation in C666-1 NPC xenografts." (PMID 28157708, 2017). "Our initial insight was that constant drug combination strategies that guarantee progression free response for tumor cell populations with considerable heterogeneity and/or MET activation, required EGFR TKI concentrations that were considerably higher than are typically clinically feasible." (PMID 28287179, 2017).
tumor (continued). "In vitro and in vivo studies with the single-arm EGFR or c-Met versions of JNJ-61186372 identified that the Fc-activity of JNJ-61186372 is mediated by binding of the anti-EGFR arm and required for inhibition of EGFR-driven tumor cells." (PMID 27786612, 2017). "Alcohol may initially activate EGFR/ErbB2 and/or induce ROS, which stimulate critical signaling components, such as p38 MAPK, Wnt/GSK3β/β-catenin, and TLR4/Nanog, as well as alter tumor microenvironment, resulting in the promotion of CSCs." (PMID 29156633, 2017). "No cytotoxicity was observed on EGFR-positive cells or EGFRvIII-negative cells demonstrating the high selectivity of EGFRvIII/CD3 TandAbs for the tumor-specific EGFRvIII." (PMID 28596941, 2017). "The lack of mutations in KRAS, EGFR and ALK genes in CRC cultured tumor specimens suggested that the cells growing in CRC conditions are mostly non-malignant." (PMID 28052041, 2017). "Molecular genetic analysis was performed on the previously resected left upper lobe tumour with pyrosequencing showing an EGFR deletion in exon 19 (c.2235_2249del15) and negative IHC for ALK." (PMID 28347348, 2017). "Dual EGFR and MEK and/or mTOR inhibitors showed improved response in tumor models harboring aberrant biomarkers, such as RAS, BRAF and PIK3CA mutations, suggesting that they might prevent the activation of resistance pathways." (PMID 28002810, 2017). "This suggests that miR-671 diminishes the inhibition of miR-7 expression through ciRS-7; improves the miR7 level in tumor cells; contributes to the increase of downstream target oncogenes, such as EGFR and XIAP; and promotes vascularization, metastasis and reproduction of tumor cells." (PMID 28143578, 2017). "This tumour microenvironment can exert pro- and/or anti-tumorigenic actions, depending on context, while malignant cells create a permissive and supportive tumour matrix by secreting stroma-modulating growth factors, including PDGF, EGFR, VEGF, and TGF-β." (PMID 28558757, 2017). "We show that ENb-TRAIL has therapeutic efficacy in tumor cells from different cancer types which do not respond to either EGFR antagonist or DR agonist monotherapies." (PMID 28572590, 2017). "In this context, surprisingly, a restrospective study found the majority of CNS and leptomeningeal metastases to be negative for EGFR T790M despite of T790M positivity in the extracranial tumor (spatiotemporal heterogeneity)." (PMID 28243590, 2017). "In the blocking experiments, the tumor uptake of 177Lu-PCTA-cetuximab was markedly reduced by administration of excess cold cetuximab, indicating that 177Lu-PCTA-cetuximab was specifically localized in EGFR expressing SNU-1066 HNSCC xenograft." (PMID 29190900, 2017). "Four patients died of non-lung-cancer-related disease without tumor recurrence (two in the EGFR mutant group and two in the wild-type group)." (PMID 29065153, 2017). "The PDECX model 1T0327 with overexpression of both EGFR and FGFR1 protein showed only modest tumor growth inhibition to theliatinib treatment suggesting that FGFR1 overexpression could diminish theliatinib efficacy." (PMID 28881608, 2017). "In contrast, EGFR lacked a tumor-specific expression pattern and therefore the ability to distinguish between malignant and normal tissues." (PMID 28841839, 2017). "We performed ANCOVA with dm and cell treatment as predictors of biosensor lifetime to statistically assess how the proximity of macrophage to tumour cells affects EGFR activity in the presence or absence of TKI treatment." (PMID 28166195, 2017). "Importantly, in accordance with the results in vitro, the cellular signals including p-EGFR, p-AKT, p-ERK and p-FAK in the 2FF-treated tumor tissues were decreased compared with those in the controls treated without 2FF." (PMID 28912543, 2017). "MATN2 traps EGFR at the cell surface for enhanced activation by EGF, driving tumour progression." (PMID 28416796, 2017).
tumor (continued). "Disease control (lasting ≥ 6 months) with no significant increment in tumor burden in comparison with earlier assessment and asymptomatic status of pre-existing item (Symptom scored ≤ 1) with EGFR-TKI treatment is defines as gradual progression." (PMID 29050366, 2017). "Indeed, genetic alterations in the EGFR, FGFR3, and RAS pathways are typical of tumor initiation and progression in bladder." (PMID 26925094, 2016). "Thus, when targeted NGS results were compared to results obtained by real-time PCR for tumor samples from patients with NSCLC, the two methods had high concordance rates for the three genes tested: 96.3% for EGFR, 98.7% for KRAS, and 100% for BRAF." (PMID 27589834, 2016). "Our study found less membranous E-cadherin, more cytoplasmic vimentin, and more membranous EGFR in primary tumor samples with LNM than in those without LNM." (PMID 27172790, 2016). "This analysis showed that the signaling behavior and tyrosine phosphorylation levels are heterogeneous across different tumor lines and downstream signaling is not related in any obvious way to EGFR status for the analyzed lines." (PMID 27354287, 2016). "TUSC2 nanovesicles combined with erlotinib, an inhibitor of activated epidermal growth factor (EGFR), synergistically inhibited tumor growth and metastases in NSCLC cells with wildtype EGFR by abrogating resistance pathways related to FGFR2 and mTOR activation." (PMID 27845352, 2016). "Although miR‐7 exerts a more profound suppression of EGFR signaling, the tumour suppressive effects of miR‐7 were not significantly greater than those of miR‐134 (data not shown)." (PMID 27241841, 2016). "As with patient 6, the presence of single EGFR p.L858R does not provide conclusive evidence that tumours 1 and 2 of patient 5 were clonally related." (PMID 27767028, 2016). "On the contrary, EpCAM and EGFR were found to be expressed at high rates (high percentage) and with moderate to high Median Fluorescence Intensity (MFI) in most of the analysed tumour cell lines." (PMID 27711186, 2016). "Differently, EGFR ECD mutant subclones do not pre-exist in WT CRC but emerge during drug-driven tumour evolution and confer a fitness advantage throughout anti-EGFR treatment." (PMID 27929064, 2016). "Tumor genotype was established using Sequenom Mass ARRAY; EGFR, PTEN, cMET and AXL expression was assessed by immunohistochemistry, circulating markers of EGFR activation (TGF-α, amphiregulin, epiregulin, EGFR ECD) by ELISA and EGFR, MET copy number by FISH." (PMID 27028852, 2016). "Likewise, we screened the prime targets of these miRNAs (EGFR and PIK3CA) and discovered that they were both significantly upregulated in the tumor tissues." (PMID 27095166, 2016). "Binding properties of the unlabelled nanobodies D10 and F5 were compared to the ones of radiolabelled nanobodies 99mTc-D10 and 99mTc-F5 on endogenously expressed EGFR on A431, MDA-MB-231 and MDA-MB-468 tumour cells using flow cytometry after decay of the radioactivity." (PMID 26912069, 2016). "For cell survival of tumor cells, the signal pathway through HGFR could be different from EGFR and HER2 pathways in terms of indispensability." (PMID 27834817, 2016). "Here we demonstrate that combined MET and EGFR inhibition with either MGCD265 and erlotinib treatment or crizotinib and erlotinib treatment were highly effective at abrogating tumor growth and significantly decreased the variability in treatment response compared to monotherapy." (PMID 27655711, 2016). "After gefitinib treatment, the tumor volumes of MDA-MB-231/E1A/AXL-injected mice were higher than those of MDA-MB-231/E1A/Ctrl-injected mice, suggesting that downregulation of AXL is essential for E1A-mediated sensitization of EGFR-TKI." (PMID 27590506, 2016). "Tandem trimerbodies were further analyzed by flow cytometry for binding to EGFR-negative and EGFR-positive tumor cell lines." (PMID 27345490, 2016).
tumor (continued). "However, in the tumor tissues originated from the LV-control transfected PC9, although the activation of EGFR was obviously suppressed, the phosphorylation of PI3K and AKT was inhibited only slightly under the treatment of gefitinib." (PMID 27690301, 2016). "If IFN-γ can inhibit EGFR/Erk1/2 and Wnt/β-catenin signaling pathways, as was reported, lack of IFN-γ receptor would be expected to lead to an upregulation of those pathways in tumor cells, consequently driving the proliferation of tumor cells." (PMID 27286456, 2016). "Proteomic analysis of AKT, ERK1/2, MEK1/2, EGFR and c-MET phosphorylation was conducted for normal and tumor ischemic tissue samples from all 20 patients, and relative quantification of phosphorylation was calculated by determining the AUC of annotated peaks in relation to each other (% area)." (PMID 26742633, 2016). "In LAC cells with acquired resistance to Epidermal Growth Factor Receptor Tyrosin Kinase Inhibitor (EGFR-TKI), we found that a part of tumor cells were much more sensitive to HH or HGF/MET inhibitors, suggesting an oncogenic addiction shift from EGFR to HH and HGF/MET pathways." (PMID 27015549, 2016). "After binding to EGFR, AREG stimulation of the intrinsic tyrosine kinase activity of EGFR induces a complex cascade of phosphorylation and activation events that determine cell proliferation, differentiation, and tumor development." (PMID 27391842, 2016). "Moreover, aberrant regulation of the epidermal growth factor receptor (EGFR) signaling pathway was commonly found in NPC cells, which was related to tumor recurrence, metastasis, and poor survival." (PMID 27149165, 2016). "EGFR expression was also an unfavourable prognostic factor, although not independent from other factors, in intestinal type tumours." (PMID 27070783, 2016). "In addition, in vivo xenograft mice model demonstrated that the tumor formation and angiogenesis were strongly suppressed by combination treatment of anti-VEGF and anti-EGFR antibodies." (PMID 27729020, 2016). "Our past miRNA studies of BC cells showed that clustered miRNAs (including miR-1/133a (targeting TAGLN2), miR-23b/27b/24-1 (targeting EGFR, MET, and FOXM1), and miR-195/497 (targeting BIRC5 and WNT7A)) act as tumor-suppressive miRNAs through their regulation of several oncogenic genes and pathways." (PMID 27072587, 2016). "In order to optimize EGFR imaging and visualize EGFR expression in vivo we developed the EGFR PET tracer 89Zr-imgatuzumab and examined the influence of sEGFR on 89Zr-imgatuzumab tracer kinetics and tumor uptake in multiple xenograft models using microPET imaging." (PMID 27602494, 2016). "In tumours containing catalytically inactive PTEN, the control over Rab7-dependent EGFR endosomal degradation may be lost leading to uninterrupted growth signalling, and this could have important implications for tumour progression." (PMID 26869029, 2016). "Here, we performed a longitudinal survey of circulating miR-1246 and miR-1290 in the same individuals to assess variation in their levels in response to ongoing EGFR tyrosine kinase inhibitor (TKI) treatment, which is a standard of care for NSCLC patients with tumours harbouring mutant EGFR." (PMID 27325363, 2016).
tumor (continued). "Patients progressing on first-generation EGFR inhibitors are expected to undergo tumor re-biopsies; and tumor heterogeneity and false-negative results make future treatments more challenging." (PMID 27200298, 2016). "Using NSCLC cell lines with differential EGFR status, we examined the potency of PA-MSHA (Pseudomonas aeruginosa-mannose-sensitive hemagglutinin) in combination with Gefitinib on proliferation, apoptosis, cell cycle arrest, EGFR signaling and tumor growth." (PMID 27283902, 2016). "EGFR expression was similar in pancreatobiliary (PB) and intestinal (I) type tumours, but high HER2 and HER3 expression was significantly more common in I-type tumours." (PMID 27070783, 2016). "In contrast to trastuzumab, the anti-tumor activity of lapatinib is based solely on the intracellular inhibition of cell-signaling by competing with ATP for the ATP-binding domain in the cytoplasmic tail of the tyrosine kinase receptor – mostly HER2 and EGFR." (PMID 26623720, 2016). "Interestingly, phosphorylation of ERK1/2 and AKT downstream effectors were inhibited by restoration of miR-206 in cancer cells, indicating that tumor-suppressive miR-206 inhibited dual signaling networks activated by MET and EGFR." (PMID 26646588, 2016). "ALK-positive patients were more likely to have a small tumor (≤ 3 cm), compared to EGFR-positive patients, although this difference was not statistically significant (p = 0.06)." (PMID 27518729, 2016). "Particularly, SKCXCR2-derived tumor tissues induced higher activation of the NF-κB signaling pathway, while having no change in EGFR-activated signaling such as Raf, MEK, Akt, mTOR and Erk compared to SKA-derived tumors." (PMID 27723802, 2016). "Significant EGFR and HER-2 mRNA and protein expressions in in situ carcinomatous sites relative to invasive areas suggest that these molecules play a role during the early stages of tumor progression." (PMID 27490467, 2016). "Inhibition of EGFR in HCT116 cells dramatically reduced TAM polarization and reduced tumor growth." (PMID 27683110, 2016). "Conversely in EGFR expressing tumours HNC (CAL-27, SCC-61, SCC-35 and SQ-9G), NSCLC (A549) and colorectal (HCT-116), tumour xenografts showed Cy5 signal accumulation for up to 72 h after C-MMAE injection while tumours from low EGFR LN-229 did not." (PMID 27698471, 2016). "Based on the results, we concluded that the addition of PPV on docetaxel treatment did not improve tumor response and survival for wild type EGFR advanced NSCLC as a second- or third-line setting." (PMID 27274999, 2016). "This signature correlated with lack of response to EGFR targeting also in patient-derived tumour xenografts." (PMID 27708224, 2016). "Moreover, cotransfection with EGFR, AKT2, or CCND1 not only counterbalanced the tumor suppressor effects of miR-2861, but also promoted cancer cell growth and enhanced cell invasion ability." (PMID 27364926, 2016). "Besides, to overcome sensitivity to EGFR-targeted therapies, some other tumors undergo a phenomenon similar to epithelial to mesenchymal transition (EMT), where the tumor can even suffer a change in histology, from NSCLC to SCLC." (PMID 27528792, 2016). "Significant EGFR and HER-2 mRNA, and protein expression in in situ carcinomatous sites relative to invasive areas suggest these molecules play a role during the early stages of tumor progression." (PMID 27490467, 2016). "In addition, these assays require separate runs for the detection of p.T790M and other EGFR mutations and therefore may not be suitable for comprehensive mutational profiling in core biopsy or fine needle aspiration specimens where tumor tissue is often limited." (PMID 27304188, 2016).